ACTA2 (actin alpha 2, smooth muscle)
Diseases named in the same sentence as ACTA2 in open-access papers (continued):
Sharing a sentence is not in itself a finding about the gene and the disease.
asthma (5 papers, 2013 to 2025). "ACTA2 has been implicated in TGF-β-induced epithelial-to-mesenchymal transition (EMT) in bronchial cells in a cellular model of asthma, and in numerous other models of tissue fibrosis." (PMID 23418565, 2013). "It is possible that the reduction of ACTG1 in asthma may promote the upregulation of ACTA2, and probably ACTB, thereby enhancing AHR through the activation of inhibitory pathways that prevent muscle relaxation, such as those regulated by ROCK." (PMID 40980809, 2025). "In conclusion, our findings provide evidence for the differential involvement of actin cytoskeletal isoforms in the regulation of ASM contraction and their association with AHR in asthma, identifying ACTB and ACTA2 as a key determinant in the disease’s pathophysiology." (PMID 40980809, 2025). "In conclusion, our study revealed that BT was effective in 81% of patients irrespective of asthma endotypes and was associated with a reduction in ACTA2 and an increase in FAP, COL1A1, COL1A2 and CD68 gene expression." (PMID 35534846, 2022). "Therefore, the regulation of not only ACTA2 but also ACTG1 may be involved in the increased contraction of ASM in asthma." (PMID 40980809, 2025). "This study confirmed the expression of peptides corresponding to ACTA2, ACTB, ACTG1, MYH11, FLNA, MYL9, and TAGLN in both control guinea pigs and the asthma model." (PMID 40980809, 2025). "MYH11, MYL9, ACTA2, and TAGLN are involved in various pathologies, including the excessive contraction observed in ASM in asthma." (PMID 40980809, 2025). "In asthma model guinea pigs, ACTG1 expression significantly decreased compared to controls, while the expression levels of ACTB, ACTA2, and MYL9 significantly increased (p < 0.01, n = 5, each group)." (PMID 40980809, 2025). "Based on immunohistochemistry data, the interactomes related to the expression of MYH11, MYL9, ACTG1, ACTA2, ACTB, TAGLN, and FLNA in the bronchial smooth muscle of guinea pigs in an asthma model were generated." (PMID 40980809, 2025). "ACTG1 exhibits a differential behavior compared to ACTB and ACTA2 in the present study, as its decrease correlates with AHR in asthma." (PMID 40980809, 2025). "Thus, this study demonstrated that the expression of the main smooth muscle actins, namely, ACTA2, ACTB, and ACTG1, was modified in the bronchial smooth muscle—a crucial tissue in asthma —of guinea pigs in an asthma model." (PMID 40980809, 2025). "The rise in ACTA2 expression, an actin that interacts directly with myosin filaments during contraction, has been previously observed in response to excessive ASM contraction during AHR in asthma patients, reinforcing the relevance of this protein in the disease’s pathophysiology." (PMID 40980809, 2025).
cerebrovascular disease (5 papers, 2015 to 2024). "In some cases, the pathogenic variant of ACTA2 is associated with intracranial aneurysms and Moyamoya-like cerebrovascular disease, so the patient will be undergoing a cranial CT scan." (PMID 39685614, 2024). "We present the first integrated analysis of a severely compromised patient with the R179H mutation and define the arterial pathology of ACTA2-related cerebrovascular disease." (PMID 26637293, 2015). "Based on arteriographic findings, a distinct cerebrovascular disease has been proposed for ACTA2 heterozygous patients carrying the R179H mutation." (PMID 26637293, 2015). "miRNA 145 is established to suppress stem cell pluripotency markers, such as OCT4, SOX2, and NANOG, and increases levels of SMA in SMCs; thus, disruption of this miRNA likely causes MMD-like cerebrovascular disease through a similar mechanism to ACTA2 p.R179 variants." (PMID 37886459, 2023). "In conclusion, these characteristic clinical and pathologic findings confirm ACTA2-related cerebrovascular disease as a new cerebrovascular disorder for which new therapeutic strategies need to be designed." (PMID 26637293, 2015). "The assessment of the Acta2 mutant mice show that these techniques can successfully detect cerebrovascular disease in mouse models of human disease." (PMID 25985192, 2015).
Cirrhosis (5 papers, 2024 to 2026). A chronic disorder of the liver in which liver tissue becomes scarred and is partially replaced by regenerative nodules and fibrotic tissue resulting in loss of liver function. "Analyzing the cirrhosis dataset (GSE25097) revealed that the expression of SLC27A5 was negatively correlated with that of fibrosis‐related genes such as ACTA2, COL1A1, and COL3A1." (PMID 37957540, 2024).
idiopathic pulmonary fibrosis (5 papers, 2021 to 2024). Idiopathic pulmonary fibrosis (IPF) is a nonneoplastic pulmonary disease that is characterized by the formation of scar tissue within the lungs in the absence of any known cause. "Idiopathic Pulmonary Fibrosis (IPF) is caused by uncontrolled stimulation of fibroblasts, leading to the accumulation of ACTA2, collagen and fibronectin in the extracellular matrix, resulting in loss of tissue architecture and functioning." (PMID 33513839, 2021). "Lung tissues from IPF (idiopathic pulmonary fibrosis) patients display excessive accumulation of ACTA2+ myofibroblasts, which can deposit extracellular matrix (ECM) proteins, leading to the destruction of the lung architecture." (PMID 38094618, 2023).
Moyamoya disease (5 papers, 2015 to 2025). Moyamoya disease (MMD) is a rare intracranial arteriopathy involving progressive stenosis of the cerebral vasculature located at the base of the brain causing transient ischemic attacks or strokes. "While in the past cerebrovascular abnormalities associated with ACTA2 variants were regarded as a variant of Moyamoya angiopathy (MMA), in recent years — due to its unique radiologic and histopathologic features — ACTA2 cerebral arteriopathy has been established as a novel entity independent of MMA." (PMID 37587538, 2023). "ACTA2 mutations are associated with structural disruption and functional impairmentof contractile proteins, and predispose to a variety of diffuse vascular diseasesincluding TAAD, CAD, ischemic strokes, and Moyamoya disease." (PMID 26934405, 2015). "Studies on ACTA2 mutations have demonstrated that mutationcarriers show various vasculopathies, including premature onset of coronary arterydisease (CAD), premature ischemic strokes (including Moyamoya disease), and familialthoracic aortic aneurysms and dissections (TAADs)." (PMID 26934405, 2015). "Certain ACTA2 variants are associated with a distinctive cerebrovascular phenotype characterized by an anomalously straight course of intracranial arteries, dilatation of proximal ICA and stenosis of distal ICA, in the absence of a compensatory basal collateral network found in Moyamoya disease." (PMID 37587538, 2023).
Obesity (5 papers, 2019 to 2025). Accumulation of substantial excess body fat. "Obesity-related increase of Acta2 mRNA in both animal models was associated with higher Acta2 protein levels in the HFD model but not the ob/ob mice illustrating that posttranslational regulation of Acta2 expression varies between these two models." (PMID 37884762, 2024). "Although the role of ⍺-SMA+ myofibroblasts in WAT fibrosis is not completely understood, studies have shown the presence of ⍺-SMA+ ASC in WAT isolated from obese individuals, as well as increased WAT Acta2 expression in mouse models of diet-induced obesity." (PMID 40774386, 2025). "These genes were also examined in female placentae, however, only Pi15, Nup210, Acta2, Rnf222, and Muc15 were significantly modulated by obesity." (PMID 32203108, 2020). "When comparing both timepoints, most transcripts exhibited a different expression pattern, including Muc15, Cnn1, and Acta2 which were not affected by obesity at E13." (PMID 32203108, 2020).
Patent ductus arteriosus (5 papers, 2013 to 2024). In utero, the ductus arteriosus (DA) serves to divert ventricular output away from the lungs and toward the placenta by connecting the main pulmonary artery to the descending aorta. "Additional symptoms that can be found in ACTA2 mutation positive patients include persistent ductus arteriosus, bicuspid aortic valve, iris flocculi, and cerebrovascular accidents." (PMID 22801769, 2013). "Interestingly, ACTA2-mutation carriers also presented with other vascular abnormalities, including livedo reticularis, iris oculae, and patent ductus arteriosus (PDA)." (PMID 40337343, 2024). "This notion is compatible with mutations of ACTA2 or MYH11, which display severe vascular consequences including patent ductus arteriosus and familial thoracic aortic dissection." (PMID 34145342, 2021). "In addition, ACTA2 mutations have been identified in 14 % of TAAD patients, while MYH11 mutations have been found in TAAD patients with persistent ductus arteriosus." (PMID 22801769, 2013). "Various genes, including ACTA2, MYH11, MYLK, and PRKG1, have been identified to be responsible for hereditary non-syndromic TAAD, which is typically accompanied by patent ductus arteriosus (TAAD/PDA)." (PMID 38773466, 2024).
breast tumors (4 papers, 2016 to 2021). "POU1F1 and ACTA2 protein (α-SMA) expression were also evaluated in seven primary cultures of human breast tumors." (PMID 33714987, 2021). "Our study demonstrates a clear relationship between POU1F1 and α-SMA in breast tumors as well as the clinical prognostic value of both POU1F1 and ACTA2 mRNA expression." (PMID 33714987, 2021).
cardiac hypertrophy (4 papers, 2015 to 2025). "Similar trends were also observed in other markers of pathological cardiac hypertrophy such as Ctgf (connective tissue growth factor), Mmp2 (matrix metalloproteinase‐2) and Acta2 (α‐smooth muscle actin; P=0.080 by Šídák's post hoc test)." (PMID 39921516, 2025). "Consistent with their enlarged hearts, dKO mice showed significant increases in the expression of the cardiac hypertrophy genes Acta2 (P≤0.05) and Myh7 (P≤0.0005)." (PMID 38770680, 2024).
dissection (4 papers, 2019 to 2025). The separation and isolation of tissues for surgical purposes, or for the analysis or study of their structures. "Type A aortic dissection always requires immediate surgical intervention whether or not a pathogenic ACTA2 variant is present." (PMID 31752940, 2019).
keloid (4 papers, 2021 to 2026). An irregularly shaped, elevated mark on the skin caused by deposits of excessive amounts of collagen during wound healing. "We also analyzed the expression of ADAM12 and α-SMA (encoded by ACTA2) in keloid and normal scar tissues by immunofluorescence." (PMID 34140509, 2021). "In vitro phenotypic assessment using the intact C1Q complex showed that C1Q increased ACTA2 expression in primary keloid fibroblasts, whereas RAP attenuated this effect; COL1A1 and POSTN showed no consistent induction." (PMID 42278663, 2026). "Furthermore, CD31 + ACTA2+ microvascular structures were abundantly detected in keloid skin dermis and in the hypodermal region of the scleroderma skin sections." (PMID 39072821, 2025). "ScRNA-seq analysis identified consistent expression patterns for TEM1, ACTA2, COL1A1, FN1, TGFBR1, and TGFBR2 in distinct fibroblast subsets of both keloids and hypertrophic scars." (PMID 38254097, 2024).
steatosis (4 papers, 2020 to 2025). Increased lipid within the cytoplasm of cells. "Steatosis, collagen deposition, and ACTA2 expression increased over time during the 12 weeks of CDAA-HF feeding." (PMID 40002688, 2025). "The expression profiles of profibrotic genes such as CYGB, ACTA2, PCDH7, DES, COL1A1, and COL1A3 were also significantly up‐regulated in the co‐culture NASH model, when compared with the steatosis model." (PMID 31909357, 2020).
aneurysmal disease (3 papers, 2022 to 2025). "This analysis revealed striking differences in the behavior of each subset, which included opposite direction of change for transcripts derived from genes critically involved in aneurysmal disease such as Myh11, Acta2, Flna, Smtn, and Tagln." (PMID 35463747, 2022). "However, despite causing cardiovascular abnormalities, complete loss of ACTA2 and MYH11 protein expression does not cause aneurysm formation in mice which makes these models unsuitable for studying ACTA2 and MYH11 induced aneurysmal disease development." (PMID 35492343, 2022).
familial thoracic aortic aneurysm (3 papers, 2018 to 2024). "Future studies also have to investigate whether the observed miRNA expression profiles are specific to MFS or also relate to other syndromes with familial thoracic aortic aneurysm like Loeys–Dietz syndrome, Shprintzen–Goldberg syndrome or mutations in ACTA2." (PMID 29530068, 2018).
glioblastoma (3 papers, 2009 to 2025). The most malignant astrocytic tumor (WHO grade IV). "Shorter overall survival of newly diagnosed glioblastoma patients was confirmed for those patients who had high intratumoral expression of actin alpha 2 (ACTA2), which was one of the highly expressed CAF markers in this study." (PMID 38275375, 2023). "An important recent finding confirming the tumor-supportive role of CAFs is the strong expression of the CAF marker actin alpha 2 (ACTA2) in glioblastomas, and the amount of ACTA2 expression inversely correlates with overall patient survival." (PMID 38275375, 2023).
Infertility (3 papers, 2018 to 2023). "In this way, downregulation of Acta2 gene expression can be associated with the abnormal uterine contractility which may contribute to endometrium-factor induced infertility." (PMID 37731819, 2023). "Hence, ATP-mediated ACTA2 and CNN1 decreases in HTPCs could be first steps en route to infertility." (PMID 29362497, 2018).
ischemic stroke (3 papers, 2015 to 2023). A stroke disorder caused by obstruction of blood flow to the brain, due to thrombotic (local blood clot formation) or embolic (due to a blood clot or other material traveling from another site) event. "ACTA2 gene mutationscause a diversity of diffuse vasculopathies such as thoracic aortic aneurysmsand dissections as well as occlusive vascular diseases, including prematurecoronary artery disease and ischemic stroke." (PMID 26934405, 2015). "TAADwas the primary vascular disease in ACTA2-mutation carriers, some of which alsohad premature CAD, ischemic strokes and multiple vascular diseases, includingMoyamoya disease." (PMID 26934405, 2015).
liver cancer (3 papers, 2022 to 2025). An epithelial or non-epithelial malignant neoplasm that arises from the liver. "The expression of inflammation-related marker TNF-α, EMT-related marker ACTA2, and proliferation marker Ki67 was approximately 25-fold, 3-fold, and 2-fold higher in patient-derived liver cancer organoids, respectively, compared to normal liver organoids." (PMID 40852642, 2025). "EMT- and metastasis-related markers (ACTA2 and PDGFRB) were expressed at similar levels in the Matrigel group, the Liver ECM group, and liver cancer tissue." (PMID 40852642, 2025). "In addition, the hepatic stellate cells of liver cancer tissues had higher expression of activated markers including COL3A1 and ACTA2 than cells of noncancer tissues, which suggested the hepatic stellate cells of cancer tissues resembled aHSCs." (PMID 38036508, 2023).
mesothelioma (3 papers, 2016 to 2023). A usually malignant and aggressive neoplasm of the mesothelium which is often associated with exposure to asbestos. "The top four genes (COL5A2, ITGAV, SPARC, and ACTA2) associated with the strongest correlation with EMT Top50 mesenchymal genes were selected for further analysis, confirming their prognostic importance in mesothelioma and other solid tumors using the TCGA database of online platforms." (PMID 36901697, 2023). "Besides a few sporadic studies, this may be the first study to identify COL5A2, ITGAV SPARC and ACTA2 as a panel of emerging EMT genes in mesothelioma." (PMID 35046456, 2022).
occlusive vascular disease (3 papers, 2015 to 2023). "This is further supported in the literature, as Acta2 mutations in SMCs have been linked to occlusive vascular disease via increased SMC proliferation." (PMID 38060277, 2023).
osteosarcoma (3 papers, 2020 to 2023). A usually aggressive malignant bone-forming mesenchymal neoplasm, predominantly affecting adolescents and young adults. "PODN was regarded as a potential biomarker for the diagnosis and prognosis of osteosarcoma, ACTA2, COL6A1, FAP, OLFML2B and COL6A3, can be used as potential prognostic indicators for osteosarcoma." (PMID 34273970, 2021). "ACTA2, or actin alpha 2, was found to be a potential prognostic indicator for osteosarcoma." (PMID 37681913, 2023). "Finally, it was determined that PODN has functional relevance in osteosarcoma and additional genes (ACTA2, COL6A1, FAP, OLFML2B and COL6A3) have prognostic significance for osteosarcoma." (PMID 34273970, 2021). "Among the DEPs identifying oseoblastic and telangiectatic osteosarcoma subtypes are CAT, FGA, SLC4A1, and ACTA2." (PMID 37681913, 2023). "Five of the seven immune-related genes (CDCA7, GZMA, SLC7A7, VAMP8, and EVI2B) were highly expressed in the osteosarcoma group, while two of these immune-related genes (IFITM3 and ACTA2) were lowly expressed." (PMID 33384961, 2020). "Furthermore, ACTA2, COL6A1, FAP, OLFML2B and COL6A3, can be used as prognosis biomarkers for osteosarcoma." (PMID 34273970, 2021). "The heatmap of these seven immune-related genes expression level in GSE42352 indicated that five of these genes (CDCA7, GZMA, SLC7A7, VAMP8, and EVI2B) were highly expressed in the osteosarcoma group, but two of these genes (IFITM3 and ACTA2) were highly expressed in the normal group." (PMID 33384961, 2020).
scleroderma (3 papers, 2023 to 2025). Scleroderma is a rare autoimmune connective tissue disorder characterized by abnormal hardening of the skin and, sometimes, other organs. "EGR3 is upregulated in the fibrotic dermis of mice with scleroderma, and increased EGR3 expression contributes to the upregulation of fibrotic genes such as ACTA2 and COL1A1." (PMID 37957540, 2024). "In contrast, activated sublining FLS were transcriptionally similar to ACTA2+ myofibroblasts and WNT5B+ fibroblasts in the colon as well as two populations of dermal fibroblasts expanded in scleroderma as compared to healthy skin (CCL19+APOE+CXCL12+ and SFRP2hiPRSS23+THY1+)." (PMID 37277655, 2023).
Achalasia (2 papers, 2017 to 2023). A disorder of esophageal motility characterized by the inability of the lower esophageal sphincter to relax during swallowing and by inadequate or lacking peristalsis in the lower half of the body of the esophagus. "Several susceptibility genes have been identified for MMD: MMD-2 (gene: RNF213), MMD-5 (ACTA2), and MMD-6 with achalasia (GUCY1A3)." (PMID 28617845, 2017).
Alagille syndrome (2 papers, 2023). "The number of patients with associated SCD, NF1, Down syndrome, cranial radiation, congenital cardiac abnormality, renal artery stenosis, ACTA2 mutation, and Alagille syndrome were 131 (42.5%), 47 (15.3%), 40 (13.0%), 24 (7.8%), 18 (5.8%), 6 (1.9%), 3 (1.0%), and 3 (1.0%), respectively." (PMID 36752913, 2023).
aniridia (2 papers, 2019 to 2024). Aniridia is a congenital ocular malformation characterized by the complete or partial absence of the iris. "The p.Arg179His hotspot variant in ACTA2 was identified in a patient with bilateral aniridia (A141)." (PMID 38459225, 2024).
breast invasive carcinoma (2 papers, 2022 to 2023). "In several malignancies, including pancreatic ductal adenocarcinoma and invasive breast cancer, ACTA2 has been related to tumor-associated fibroblasts, and has a function in cell shape, cellular integrity, and motivation." (PMID 37274283, 2023).